CXCL12 (C-X-C motif chemokine ligand 12)
Diseases named in the same sentence as CXCL12 in open-access papers (continued):
Sharing a sentence is not in itself a finding about the gene and the disease.
tumor (continued). "Our study establishes ASC as the source of CXCL12 driving tumor aggressiveness and outlines an approach to treatment of carcinoma progression." (PMID 33753872, 2021). "In a Kaplan–Meier analysis, the CXCL12 tumor expression significantly predicted disease-free, progression-free, and overall survival." (PMID 34834449, 2021). "The importance of CXCL12/CXCR4 in intraosseous tumor cell dissemination is further underpinned by the observation that inhibition of CXCR4 remobilizes PrCa DTCs back into circulation, thus possibly increasing their vulnerability to anticancer treatment." (PMID 34064859, 2021). "NOX-A12 was developed to interfere with CXCL12 in the tumor microenvironment and in cell mobilization." (PMID 34503058, 2021). "On the other hand, CXCL12 also mediates the tumor inflammatory responses by interacting with various immune cells, which can either promote or suppress tumor dormancy." (PMID 34712663, 2021). "These pathways are exploited during tumorigenesis, especially in the metastatic process, where CXCR4-expressing tumor cells are chemotactically homed to organs with abundant levels of CXCL12—such as the liver, bone marrow, lungs and lymph nodes." (PMID 34793563, 2021). "In primary bone site, OS epigenetically downregulates CXCL12 expression by DNMT1, impairs cytotoxic T-cell homing to the tumor site and this chemokine gradient of CXCL12 drives the metastasis of OS cells to the lung, where CXCL12 is highly expressed." (PMID 34956899, 2021). "The overexpression of CXCL12 stimulates further recruitment of TAMs into the gastric microenvironment inducing tumor cell invasion and progression of gastric carcinogenesis." (PMID 33206367, 2021). "For Ccl5, Ccl22, Ccl27a, Ccl28, and Cxcl12, chemokines known to exert pro-tumor effects, substantially higher levels were noted in the liver." (PMID 33985562, 2021). "CXCL12 is critically involved in remodeling the immune landscape of the tumor towards a more immune suppressive environment by recruiting cell populations such as TAMs and MDSCs, which promote tumor progression." (PMID 33530455, 2021). "By hindering the interaction of CXCR4-positive tumor cells with CXCL12-producing fibroblasts, AMD3100 therapy in a pancreatic cancer model induced rapid T-cell accumulation among cancer cells and acted synergistically with anti-PD-L1." (PMID 34575965, 2021). "CXCL12 and Wnt5a were expressed in the cytoplasm of tumor-adjacent fibroblasts and the GC cells, respectively." (PMID 33854601, 2021). "CXCR4 positive tumor cells metastasize to organs with high expression of CXCL12, such as lymph nodes, liver, lungs, and bone marrow." (PMID 33710803, 2021). "The role of CXCR4, who functions through combing its cognate chemokine ligand CXCL12 to orchestrate cancer cells directly or through inducing angiogenesis and recruiting immune cells indirectly, is broadly concerned in multiple tumour‐promoting processes." (PMID 34170080, 2021). "This sustains and prolongs the pro-tumoral activity of CXCL12 on leukocytes, but mainly on stromal and tumor cells, which considerably favors tumor progression." (PMID 34503058, 2021). "CXCL12 expression was explored across tumor types in the TCGA database, followed by paired differential analysis." (PMID 34801033, 2021). "It has been reported that the CXCL12/CXCR4 axis is related to tumor progression, angiogenesis, metastasis, and survival." (PMID 33747044, 2021). "Both tumor genotypes showed endothelial populations that were configured to support malignancy, with increased expression of the tumor stimulating cytokine Cxcl12 and the drug efflux pump Abcb1 (aka Mdr1), compared to endothelial cells in WT cerebella." (PMID 34021242, 2021). "AOM/DSS‐induced mouse CRC contained SA‐β‐Gal and p16INK4A positive senescent tumor cells like those seen in human CRC and the p16INK4A positive senescent tumor cells secreted CXCL12 abundantly." (PMID 33643790, 2021).
tumor (continued). "Compared with CAFs from primary tumors, MAFs isolated from brain metastases secrete more CXCL16 and CXCL12, thereby attracting tumor cells to metastatic sites and promoting metastasis progression." (PMID 34112258, 2021). "Chemokine (C-X-C motif) receptor 4 (CXCR4) and its ligand, the alpha-chemokine CXCL12, has been described to play a central role in tumor growth and progression, tumor invasiveness and metastasis." (PMID 33579381, 2021). "The results showed that the expression of CXCL1-2 and CXCL12 decreased with the development of tumor, while CXCL13 was opposite." (PMID 34123826, 2021). "CXCR4 leads to enhanced proliferation, migration, and invasion of tumor cells by binding to CXCL12 and activating various downstream signaling pathways." (PMID 35111153, 2021). "Studies have demonstrated that the CXCL12 released by platelets induces leucocyte recruitment to the tumor site, such as macrophages, stimulating tumor growth and angiogenesis." (PMID 34684726, 2021). "In low- and high-CXCL12 groups, recurrence/metastasis, tumor progression and death events were 12 and 1, 10 and 1, and 9 and 0, respectively." (PMID 34834449, 2021). "CXCL12 gene expression in tumor cells is controlled by HIF-1α in direct proportion to reduced oxygen level in ischemic endothelial cells." (PMID 34200145, 2021). "Tumor and stromal cells produce CXCL12, which is the ligand of chemokine receptor CXCR4, expressed by pDCs." (PMID 34575965, 2021). "In a small pilot cohort of 22 ACC patients, CXCL12 negatively correlated with tumor size, stage, Weiss score, necrosis, and mitotic activity." (PMID 34834449, 2021). "In vivo studies in LLC1 tumor models have shown that chemotherapy-induced release of CXCL12 from neoplastic cells enhanced infiltration of TAMs that contributed to tumor relapse." (PMID 34439281, 2021). "In breast cancer, expression of CXCL12 by tumor cells increased the number of macrophages and blood vessel density, contributing to metastasis." (PMID 34209703, 2021). "Although components of exosomes and EVs are multitudinous, the most commonly used in tumor dormancy researches is miRNAs, which can regulate tumor dormancy through modulating the expression of CXCL12 and the duration of TGF-β signaling." (PMID 34712663, 2021). "The binding of CXCR4 to its ligand SDF-1 (CXCL12) stimulates tumor cell proliferation and migration by activating downstream signaling transduction pathways, including the PI3K-AKT and MAPK pathways." (PMID 34503103, 2021). "In summary, these studies show that AMD3100 is able to successfully inhibit crucial tumor-driving effector mechanisms of CXCR4/CXCL12 signaling in vitro and in vivo." (PMID 34203660, 2021). "Cultured FL BM stromal cells retained numerous features of their native counterparts, including the overexpression of CCL2, IL-8, and CXCL12, suggesting an imprinting of the stromal cells by the tumor context." (PMID 34069564, 2021). "These cells are able to produce inflammatory and chemoattracting mediators such as CXCL12 and IL-11, both of which contribute to enhanced osteoclastogenesis and tumor cell homing to bone." (PMID 34064859, 2021). "With the secretion of cytokines like CXCL12 and IL-6, CAFs regulate the recruitment of macrophages and their contribution to tumor-promoting M2 type differentiation, thus affecting innate immunity." (PMID 34692696, 2021). "Ahirwar and colleagues showed that CAFs secreted CXCL12/SDF1, generating endothelial instability and hyper-permeable vasculature, facilitating the escape of tumor cells from the primary tumor to distant organs." (PMID 34201840, 2021). "Increasing studies suggested that CXCL12/CXCR4 axis played pivotal roles in tumor growth and development." (PMID 34123594, 2021). "Combined, these clinical data suggest that, like the animal models, recruitment of WAT-derived stroma promotes cancer progression, and implicate CXCL12 as a cytokine secreted by ASC that contribute to tumor aggressiveness." (PMID 33753872, 2021).
tumor (continued). "CXCL12 directly stimulates tumor growth and also promotes angiogenesis by recruiting bone marrow-derived endothelial progenitor cells." (PMID 34681633, 2021). "Specifically, CXCL12 was prominently detected in tumor cells with uniform staining patterns within samples." (PMID 34162860, 2021). "In this study, we surprisingly found a dramatic reduction in tumor sizes in mice treated with CXCL12/CSF1 neutralizing antibodies together with anti‐PD1 antibody, and CD8+ T cell infiltration was markedly increased." (PMID 33643790, 2021). "These included C-X-C motif chemokine ligand 12 (CXCL12), c-Met, receptor tyrosine kinase-like orphan receptor 1 (ROR1), and fibronectin 1 (FN1), which are associated with activated neoplasia, invasion, migration, and metastasis." (PMID 34069906, 2021). "Inhibitors of the SDF-1 receptor CXCR4, such as AMD3100 (Plerixafor), prevent SDF-1/CXCL12-mediated recruitment of bone marrow-derived precursor cells to the tumor site." (PMID 33921099, 2021). "Other cell population like tumor associated fibroblasts can secrete proinflammatory factors like IL-6, which activates STAT3, and secrete CXCL12 that inhibit T-cells infiltration in tumors." (PMID 33477288, 2021). "Numerous studies have demonstrated that tumor cells often express high levels of chemokines, such as GM-CSF, M-CSF, and CXCL12, recruiting many monocytes from the circulation into local tumor sites." (PMID 35070992, 2021). "CXCL12 was identified as the only chemokine changed in LNCaP xenograft tumor compared to cell culture." (PMID 33808801, 2021). "CXCL12 can affect tumor cells by promoting proliferation, invasion, metastasis, stemness, and modulating the immune response." (PMID 33790943, 2021). "The interactions between tumour cells and stroma mediated through CXCL12 lead to activation of the PI3K and ERK1/2 pathways, which are associated with tumour viability and the active EMT pathway, promoting cell survival and metastasis." (PMID 34059019, 2021). "Hypoxic conditions, often present in brain tumors, induce HIF-1α expression, which further stimulates CXCL12 expression in tumor cells." (PMID 34200145, 2021). "In a murine PDAC model, it was shown that CAFs prevent CD8+ T cells from reaching the tumor cells, a mechanism mediated by production of CXCL12 that retains CD8+ T cells in the stroma via CXCR4 ligation." (PMID 34203869, 2021). "The results showed that compared with those in the control group, knockdown of CXCL12 significantly inhibited tumor growth and metastasis, and anti-PD-1 treatment further reduced tumor growth and metastasis in C57BL/6 mice." (PMID 34911533, 2021). "Treatment of orthotopic HT-29 xenografts with conventional chemotherapeutic agents resulted in a decrease in CXCR4 and increase in CD26 tumor expression, which abrogated chemotaxis towards CXCL12." (PMID 34503058, 2021). "Chemokine CXCL12 plays an important role in the communication between tumor cells and their surrounding microenvironment." (PMID 33456563, 2021). "CXCL12/CXCR4 signaling can also enhance tumor progression by attracting pro-tumoral immunosuppressive immune cells." (PMID 34503058, 2021). "DNA methyltransferase 1 (DNMT1) can impair the homing ability of cytotoxic T cells to tumor cells by down-regulating CXCL12." (PMID 34631695, 2021). "CD276-CAR NK-92 cells that were added to tumor spheroids in the presence of CXCL12 were able to migrate quickly and show high cytotoxic potential within 24 h." (PMID 33925968, 2021). "Other reports on the involvement and consequences of CD26-mediated processing of CXCL12 in a tumor setting are rather scarce." (PMID 34503058, 2021). "To ivestigate the role of CXCL12 in cell living microenvironment, we focused on the interaction between tumor cell and stromal cell." (PMID 34930323, 2021). "Similar to healthy breast tissue, healthy lung cells express CXCL12 at low to undetectable levels as compared to tumor tissue." (PMID 33530455, 2021).
tumor (continued). "Chemokines such as C–C motif chemokine ligand 2 (CCL2) and C-X-C motif chemokine ligand 12 (CXCL12) recruit MDSCs to tumor sites." (PMID 33653420, 2021). "Subsequently, the importance of the CXCL12 signaling pathway in the regulation of tumor-infiltrating CD8 + T cell migration induced by FAP + CAFs, has been confirmed in several reports." (PMID 34635121, 2021). "CXCR7 acts on tumor progression and metastases at different levels upon interaction with endogenous ligands, including CXCL12, CXCL11 and the Macrophage Inhibitory Factor (MIF)." (PMID 33937018, 2021). "In contrast, iCAF are localized distant from the tumor, express low α-SMA levels and exhibit rather tumor-promoting and immunosuppressive properties by secreting inflammatory cytokines, like IL-6, CXCL12 and Granulocyte-Colony stimulating Factor (G-CSF)." (PMID 34638420, 2021). "IF revealed CXCL12 in both PDGFRα+ and PDGFRβ+ cells in tumor stroma, as well is in the adjacent matrix and blood vessels." (PMID 33753872, 2021). "The CAF-mediated CXCL12/CXCR4 axis plays a key role in tumor cell proliferation, invasion, and migration." (PMID 34447750, 2021). "Herein, we discuss the current understanding on the role of CXCL12/CXCR4/CXCR7 cross-talk in tumor progression and immune cells recruitment providing support for a combined CXCR4/CXCR7 targeting therapy." (PMID 33937018, 2021). "Further, as a possible mechanism of tumor-to-tumor metastasis, the involvement of both C-X-C motif chemokine ligand 12/stromal cell-derived factor-1 (CXCL12/SDF-1) and C-X-C motif chemokine receptor 4 (CXCR4) is examined." (PMID 34187383, 2021). "We developed different ACC xenograft mouse models to study the RGZ effects in vivo on tumor growth and the CXCL12/CXCR4 axis in a therapeutic and a prevention setting, comparing them with MTT." (PMID 34834449, 2021). "Tumor cells have chemotactic response to CXCL12 in migration assay, and we found that Salmonella reduced tumor chemotactic response after CXCL12 treatment." (PMID 34220311, 2021). "Ulocuplumab inhibits the binding of CXCR4 to CXCL12, and has shown both in vitro as well as in vivo anti-tumor in a WM tumor xenograft model engrafted with CXCR4WHIM mutated tumor cells." (PMID 33273682, 2021). "To investigate the role of CXCL12 in cancer cell living microenvironment, we focused on the interaction between tumor cell and stromal cell." (PMID 34930323, 2021). "CAFs in the primary tumor are able to express high levels of CXCL12, CXCL1, and insulin-like growth factor 1 (IGF1)." (PMID 34064859, 2021). "CXC motif chemokine ligand 12 (CXCL12) is a chemokine produced constitutively by various types of tumor cells and stromal cells." (PMID 34659412, 2021). "We found that CXCL12 and IL7R were novel therapeutic targets for LIHC, which correlated with somatic mutations and tumor immunological microenvironment modulation." (PMID 33344233, 2020). "CXCL12 expression in the lung was second only to the heart in the tumor-bearing mice, leading to the chemoattraction of more CD62Ldim neutrophils, but these changes were blocked by a CXCL12 mAb." (PMID 33178575, 2020). "In tumor cells, CXCL12 induces transendothelial migration, and thus the metastatic spread of CXCR4+CXCR7+ cells." (PMID 32098047, 2020). "ROS activation of the CXCL-12/CXCR-4 signaling pathway contributes to a cross-talk between tumor cells and CAFs." (PMID 33585565, 2020). "Fibroblasts in cancer associated status diminish SLIT2 production and subsequently by upregulation of CXCL12 as an agitation signal, promote metastatic behavior of tumor cells." (PMID 32384110, 2020). "The results showed that CXCL12/CXCR4 axis promoted immunosuppression by increasing fibrosis of tumor cells." (PMID 32253815, 2020). "C-X-C motif chemokine 12 (CXCL12), the substrate of DPP-4, and its receptor CXCR4 have been associated with the biology of cancer, such as tumor proliferation, survival, invasion and angiogenesis." (PMID 31991851, 2020).
tumor (continued). "It promoted cell proliferation, migration, and invasion in vitro and tumor growth in vivo via the miR-370-3p/CXCL12 axis." (PMID 32943996, 2020). "The HSA microenvironment has also been shown to enhance tumor growth and promote migration of tumor cells through chemokines such as IL-8 and CXCL12 and modified sphingosines." (PMID 33208160, 2020). "Both HGF and CXCL12 (cytoplasm) expression by tumor cells were correlated to OS in univariable Cox regression analysis, and HGF remained significant in the multivariable analysis." (PMID 32188473, 2020). "Chemokine receptor CXCR4 and its ligand CXCL12 play an important homeostatic role in the homing and activation of macrophage lineage cell responses during infection and activating immune cells in tumor immune responses." (PMID 33396862, 2020). "Specific inhibition of CXCL12 and TGFβ1 in CAFs inhibited the proliferating tumor cells in the emboli highlighting the importance of CAFs in protecting tumor cells in the emboli." (PMID 33414786, 2020). "Taken together, various CXCL12-mediated T cells and tumor cells chemotaxis were connected with mTOR signaling, but mTOR interventional therapy plays a pros or cons role in different conditions of TME, and it is unclear." (PMID 32483450, 2020). "CXCR4 is highly expressed on aggressive/malignant tumor cells and plays a critical role in the homing of cancer cells to distant sites following binding to its ligand CXCL12." (PMID 32239371, 2020). "The expression of CXCR4/CXCL12 in tumors is partially dependent on the hypoxic tumor microenvironment, in a HIF-1α dependent manner." (PMID 32983169, 2020). "Activation of the CXCR4/CXCL12 pathway is considered to be a major contributor to tumor invasion of surrounding tissues." (PMID 32239371, 2020). "For example, hypoxia is a major stimulant of CXCL12, which is secreted by tumor stroma fibroblasts and is involved in the early stage of malignant transformation of OC." (PMID 32257947, 2020). "By the secretion of CXCL-12, CAFs also recruit endothelial progenitor cells to the tumor’s vicinity, thus supporting tumor vascularization." (PMID 32722054, 2020). "According to the model outputs, when a fibroblast is in normal status, SLIT2 increases and inhibits CXCL12 expression which leads to prevention of tumor growth and metastasis." (PMID 32384110, 2020). "CXCL12 was reported to attract pDCs into the tumor environment and to protect them against tumor-induced apoptosis." (PMID 33013879, 2020). "CXCL12/CXCR4 axis synergizes with CD38 to support migration as a central step in tumor disease progression." (PMID 33123122, 2020). "Meanwhile, the key components of the bone marrow niche, mesenchymal stem cells (CD45-Lin-CD34-c-kit-CD29+) and CXCL12 producing cells, were significantly decreased in the bone marrow of tumor-bearing mice." (PMID 33603745, 2020). "For example, IL-7 producing CAFs show a specific oncogenic signature, produce high levels of CXCL12 and physically interact with tumor cells." (PMID 33096815, 2020). "Insufficient tumor and vascular bed destruction can effectuate a strong hypoxic condition, which results in release of chemoattractant CXCL12." (PMID 33343570, 2020). "CXCR4-positive tumor cells migrate along the CXCL12 gradient to distant organs, such as the CXCL12-rich BM microenvironment." (PMID 32260318, 2020). "The expression of CXCR4 receptor on tumor cells aids in their colonization to organs expressing CXCL12 such as bone marrow which favors tumor cell survival and growth." (PMID 33414786, 2020). "Chemokine CXCL12 also enhances tumor vasculature permeability, facilitating colonization to distant organs." (PMID 33123472, 2020). "Among a number of chemokines and their receptors, CXCL12/CXCR4 signaling is an integral oncogenic communication network between a tumor and its stroma." (PMID 32260318, 2020).